FOXP3 (forkhead box P3)
Diseases named in the same sentence as FOXP3 in open-access papers (continued):
Sharing a sentence is not in itself a finding about the gene and the disease.
Autoimmunity (continued). "Mutation of Foxp3 gene results in fatal autoimmune disorders in human, for example, immune dysregulation, polyendocrinopathy, enteropathy, X-linked (IPEX) syndrome or in mice, for example, lymphoproliferative disorder and stable expression of Foxp3 is essential for immune homeostasis." (PMID 22737174, 2012). "Mutations of the Foxp3 gene result in immune dysregulation and multiorgan autoimmunity." (PMID 21179414, 2010). "Although, antigen-specific Tregs are more potent than polyclonal Tregs in treating ongoing autoimmunity, phenotype plasticity associated with loss of FoxP3 expression in Tregs can lead to the conversion into antigen-specific effector T cells which might exacerbate autoimmune pathology." (PMID 36049437, 2022). "These unique features prompted us to hypothesize that the DEREG model is particularly suited to study the role of Foxp3+ Treg cells in organ-specific autoimmunity in mice on a genetically susceptible genetic background, while keeping collateral autoimmune damage to a minimum." (PMID 34447385, 2021). "Thus, it seems reasonable to hypothesize that the presence of the A allele, from both FOXP3 variants, could favor autoimmunity, activity disease and development of nephritis." (PMID 33686190, 2021). "Importantly, studies of immune dysregulation, polyendocrinopathy, and enteropathy X-linked (IPEX) which are characterized by rare human autoimmune disorder and allergic inflammation elucidated that Foxp3 was specifically required for Treg cell function in asthma." (PMID 33748292, 2021). "Given that FOXP3 is the master regulator of Treg differentiation, the reduced expression of this transcription factor in response to IL-2 in cells carrying the SNP might increase the risk of autoimmunity by hampering Treg functions." (PMID 31297117, 2019). "Besides, the conditional deletion of USP7 in Tregs leads to a dramatic loss of immune regulation and to lethal autoimmunity, indicating the need to counteract the process of Foxp3 ubiquitination in order to maintain a functional and stable pool of Tregs in periphery." (PMID 31824482, 2019). "The defect of FOXP3 gene may provide a critical link between autoimmunity and immune deficiency." (PMID 30229436, 2018). "Because all of their T cells carry the maternal X, this leads to uniformly high FoxP3 protein levels, which protect against autoimmunity." (PMID 41546136, 2026). "Therapeutically targeting FOXP3 and Tregs is challenging, as disrupting their function risks compromising immune tolerance and inducing autoimmunity." (PMID 41150760, 2025). "Foxp3, the master transcription factor for regulatory T cells (Tregs), is essential for maintaining immune tolerance and preventing autoimmunity." (PMID 40723924, 2025). "Regulatory T cells (Tregs), characterized by the expression of the transcription factor Forkhead box protein 3 (Foxp3), are essential for maintaining immune tolerance and preventing autoimmunity." (PMID 40723924, 2025). "Regulatory T cells (Tregs), characterized by the transcription factor Foxp3, play a pivotal role in maintaining immune homeostasis, preventing autoimmunity, and contributing to tumor immune evasion." (PMID 41458964, 2025). "FOXP3 mutations produce intense Treg-specific dysfunction, resulting in IPEX syndrome, which is a rare early-onset condition characterised by multiorgan autoimmunity." (PMID 41226379, 2025). "SCFAs promote the differentiation and stability of FOXP3+ regulatory T cells (Tregs), which play a critical role in preventing autoimmunity by suppressing excessive immune activation." (PMID 39940777, 2025). "In preclinical antigen‐specific immunotherapy models, Foxp3− CD4+ regulatory (Tr1) T cells have been shown to suppress CD8+ T cells during the development of autoimmunity." (PMID 40623940, 2025).
Autoimmunity (continued). "While suppressor T cells use IL-10 and TGF-β signaling to promote immunological tolerance, regulatory T cells (Tregs), which are identified by their expression of FOXP3, are essential in preventing autoimmunity." (PMID 39996755, 2025). "On the other hand, in a previous study that analyzed monogenic diabetes in 64 patients diagnosed before 1 year of age, a mutation causing monogenic autoimmunity was found in 2 patients, 1 in STAT3 and the other in FOXP3." (PMID 39870583, 2025). "Several studies have shown the importance of CD4 + CD25 + Foxp3 + Tregs in restraining autoimmunity in T1D." (PMID 39738937, 2025). "Conversely, Treg cells responding to type 1 inflammation in settings of autoimmunity, viral infection, or cancer were selectively lost upon Foxp3 protein depletion." (PMID 40478934, 2025). "Foxp3+ regulatory T cells (Treg) are critical for the maintenance of self‐tolerance, and their absence or dysfunction can result in autoimmunity." (PMID 40346769, 2025). "Sustained expression of FOXP3 in Treg cells is critical for maintaining its suppressive capacity in life-threatening autoimmunity." (PMID 40804844, 2025). "In contrast, a specialized subset of T-bet+CXCR3+ TREG cells that arises in settings of autoimmunity, viral infection, or cancer was continuously dependent on Foxp3 for its maintenance." (PMID 40478934, 2025). "Mutations of Treg signature genes (FOXP3, IL2R, and CTLA4) impair Treg development and function, resulting in severe autoimmunity." (PMID 41226379, 2025). "As discussed in the next section, FOXP3+ and Tr1-based Treg cell therapies are well-suited to dampen T cell-driven autoimmunity and inflammation, but lack the ability to specifically deplete B cells." (PMID 39697333, 2024). "Studying Foxp3+ regulatory T cells (Tregs) is crucial because these cells play a pivotal role in maintaining immune homeostasis, preventing autoimmunity, and modulating the immune response in both inflammatory conditions and cancer." (PMID 39272810, 2024). "For this reason, a transgenic strategy employing FoxP3-Cre combined with Bcl6flx/flx has been widely leveraged to specifically block Tfr development, and this was reported to promote autoimmunity." (PMID 39319261, 2024). "Here we highlight the immunomodulatory mechanisms of two major CD4+ regulatory T cell types: FOXP3+ Treg cells and Tr1 Treg cells, and how their functionality can be harnessed to treat autoimmunity." (PMID 39697333, 2024). "Since the regulatory T cells (Tregs) that are governed by the Foxp3 gene play a protective role against autoimmunity, a connection between GATA3 and the regulation of Treg activity is likely mediated through GATA3’s modulation of Foxp3 expression." (PMID 39768217, 2024). "CD4 + CD25 + FOXP3 + regulatory T cells (Tregs) are essential for maintaining immune tolerance and preventing autoimmunity." (PMID 39372653, 2024). "Foxp3-expressing CD4 regulatory T (Treg) cells play a crucial role in suppressing autoimmunity, tolerating food antigens and commensal microbiota, and maintaining tissue integrity." (PMID 39882241, 2024). "GCs are controlled by specialized FoxP3+ T-follicular regulatory cells (Tfr), but their role in established autoimmunity is unclear." (PMID 39319261, 2024). "These are identified as CD4+Foxp3+, playing critical roles in the prevention of autoimmunity, the maintenance of immune homeostasis, and the suppression of anti-tumor immune responses." (PMID 38673639, 2024). "When Sin3a deletion in Foxp3+ Tregs was induced following normal pre- and postnatal development, evidence of autoimmunity developed in sLNs and lungs." (PMID 39156895, 2024). "Regulatory T cells (Tregs), a subset of CD4+T cells marked by the expression of the transcription factor forkhead box protein 3 (Foxp3), are pivotal in maintaining immune equilibrium and preventing autoimmunity." (PMID 39290699, 2024). "Developmental deletion of Sin3a from Foxp3+ Tregs resulted in the rapid onset of fatal autoimmunity." (PMID 39156895, 2024).
Autoimmunity (continued). "Restoring Foxp3 transcription in mice whose TREG cells were genetically engineered to block Foxp3 expression rescues them from severe autoimmunity as it effectively reinstates their suppressive function." (PMID 38605970, 2024). "Deficits in IL-2 signaling can precipitate autoimmunity by altering the function and survival of FoxP3+ regulatory T cells (Tregs) while high concentrations of IL-2 fuel inflammatory responses." (PMID 39704171, 2024). "Mice with Foxp3 defects develop fatal autoimmune diseases, whereas lifelong continuous expression of Foxp3 prevents the occurrence of autoimmunity." (PMID 38322264, 2024). "Mice with homozygous deletion of Sin3a in Foxp3+ Tregs developed severe autoimmunity and died within 15–22 days of birth." (PMID 39156895, 2024). "Foxp3+ TREG cells have been at the focus of intense investigation for their recognized roles in preventing autoimmunity, facilitating tissue recuperation following injury, and orchestrating a tolerance to innocuous non-self-antigens." (PMID 38605970, 2024). "Given the importance of FOXP3 in autoimmunity, this work cements DDX39B as an important guardian of immune tolerance." (PMID 37261960, 2023). "CD4+Foxp3+T regulatory cells are the key cells to inhibit autoimmunity and maintain autoimmunity tolerance." (PMID 36890410, 2023). "DNMT3B also accelerates atherosclerosis by hypermethylating the forkhead box P3 (FOXP3) promoter and decreasing FOXP3 expression in regulatory T cells (Tregs), which are cells that normally prevent inflammation and autoimmunity." (PMID 37947606, 2023). "PIM deficiency further promoted expression of the nucleus accumbens-associated protein 1 (NACC1), a TF that is upregulated under pro-inflammatory conditions and promotes autoimmunity by destabilizing FOXP3 expression and suppressing Treg-mediated tolerance." (PMID 38039135, 2023). "Forkhead box P3 (FoxP3), a distinct Treg marker, dominantly controls Treg function, maintaining suppressive capacity during autoimmunity and infections." (PMID 37892995, 2023). "This was proven via a study on the failure of Tregs’ suppression of spontaneous autoimmunity with an approximately 10-fold decrease in FoxP3 protein expression due to a change in the 3’ untranslated region (UTR) of the FoxP3 gene." (PMID 37408193, 2023). "Regulatory T cells (Tregs) expressing forkhead box P3 (Foxp3) play a key role in the establishment and maintenance of peripheral immune tolerance through the prevention and suppression of autoimmunity." (PMID 37843279, 2023). "Although it plays an important in escape mechanisms against autoimmunity, FOXP3+ Treg dampens tumor immunity." (PMID 37063922, 2023). "The tolerogenic capacity of CD4+CD25+FOXP3+ regulatory T cells (Tregs), have been extensively studied in the context of transplant rejection, autoimmunity, and cancer." (PMID 37868962, 2023). "Lkb1 has been shown to maintain the homeostasis of Foxp3+ Tregs in mice, which are essential for promoting self‐tolerance and suppressing autoimmunity." (PMID 36515008, 2023). "CD4+ Foxp3+ regulatory T cells (Tregs) are indispensable for preventing autoimmunity, and they play a role in cancer and transplantation settings by restraining immune responses." (PMID 38993904, 2023). "Given their potential to reduce the requirement for immunosuppression, CD4+CD25+FOXP3+ Tregs have been pursued for their therapeutic potential to suppress autoimmunity and to reduce or eliminate the requirement for immunosuppression after transplantation." (PMID 37874660, 2023). "Foxp3+ Tregs have a critical role in the maintenance of immune homeostasis, prevention of autoimmunity, and induction of allograft tolerance." (PMID 37633275, 2023). "T cell-specific deletion of Foxo1 led to autoimmunity because of decreasing FOXP3+ Treg cells while increasing T follicular helper in vivo." (PMID 37120440, 2023). "The role of Tregs, which depend on FOXP3 transcriptional control, on autoimmunity has been carefully documented." (PMID 37261960, 2023).
Autoimmunity (continued). "CD4+ T cells expressing FOXP3 are thought to promote immune tolerance in β-cells and, therefore, increased levels of FOXP3+ CD4+ T cells signify a reduction in autoimmunity." (PMID 37400916, 2023). "IL-2 is critical for the sustenance of Foxp3+ Treg, and its absence leads to a significant shortage of Treg cells, resulting in autoimmunity." (PMID 38004268, 2023). "In recent years, with advances in research, the regulatory mechanism of CD4+CD25+Foxp3+Treg cells in the process of controlling autoimmunity and maintaining immune tolerance has been gradually understood." (PMID 35664563, 2022). "CD4+CD45RA+CD25+Foxp3+CD127loTreg are resting thymus-derived cells, known as either nTreg or tTreg that prevent autoimmunity." (PMID 36426347, 2022). "Although the mechanism of Foxp3+ Treg cell-mediated prevention of autoimmunity by suppressing CD4+CD25− effector cells is well studied, the signals controlling the development of Foxp3+ Treg cells are still not clearly elucidated." (PMID 35563702, 2022). "CTLA4, predominantly found in intracellular vesicles in FoxP3+ T regulatory cells or activated conventional T cells, is a key regulator of autoimmunity and acts as an immune checkpoint." (PMID 36061211, 2022). "CD4+FOXP3+ Tregs are T-cells with immune suppressive activity that typically mediate peripheral tolerance and prevents autoimmunity." (PMID 35158816, 2022). "mTECs present the products of these genes on its surface as self-antigens that are required for the elimination of self-reactive T cells, or their conversion to Foxp3+ regulatory T cell lineage, both of which are required for the prevention of autoimmunity." (PMID 36231130, 2022). "In this review, we discuss the potential roles of Foxp3+ Tregs in the development of tolerance in transplantation and autoimmunity, and the available data regarding their use as a treatment modality." (PMID 36466912, 2022). "Regulatory T cells (Tregs), a subpopulation of CD4+ T cells that express transcription factor Foxp3, are central to the maintenance of immunological tolerance and prevention of autoimmunity." (PMID 35493450, 2022). "Maresin 1 (MaR1) and the EGF/c-Jun pathway have both been shown to induce miR-21, restore Treg : Teff ratios through FOXP3 induction, and reduce autoimmunity." (PMID 36032083, 2022). "CD4+Foxp3+ regulatory T cells (Tregs) play a crucial role in preventing autoimmunity and inflammation." (PMID 35603221, 2022). "Tregs, such as Foxp3-expressing CD4+ Treg cells, are central to preventing the loss of self-tolerance so that autoimmunity states can be induced." (PMID 36648885, 2022). "For instance, CD4+ Foxp3+ regulatory T cells (Treg) protecting the body from autoimmunity and immunopathology have been shown to have a much higher ceramide content than CD4+ Foxp3− conventional (Tconv) T helper cells." (PMID 35997449, 2022). "We further show that the promoting effect of NAC1 on autoimmunity is mediated through its negative regulation of the stability of Treg and FoxP3." (PMID 35767626, 2022). "It has been well established that Foxp3+ regulatory T cells (Treg cells) play a crucial role for immune repression and tolerance, protecting the body from autoimmunity and inflammation." (PMID 35860233, 2022). "Reduced frequency of CD4+CD25HIGHFOXP3+ cells and diminished FOXP3 expression in patients with Common Variable Immunodeficiency:A link to autoimmunity?" (PMID 35795667, 2022). "The first wave of Foxp3+ regulatory T cells (Tregs) generated in neonates is critical for the life-long prevention of autoimmunity." (PMID 36119090, 2022).
Autoimmunity (continued). "In line with these opposing observations, increased miR-21 expression inhibited FOXP3+ Tregs in human gastric cancer whereas it induced FOXP3 in human and mouse autoimmunity." (PMID 36032083, 2022). "Mutational inactivation of FOXP3 — which causes the loss of functional Treg, such as in IPEX syndrome — leads to severe multiorgan autoimmunity." (PMID 36346673, 2022). "The depletion of CD25+Foxp3+CD4+ Tregs leads to autoimmunity while reconstituting this population prevents autoimmune disorders." (PMID 34068092, 2021). "Converted polyclonal CD4+ T cells into FOXP3+ Tregs can be used in the context of autoimmunity or allogeneic responses." (PMID 33708227, 2021). "As such, CD25 deficiency results in the failure to produce functional Foxp3+ Tregs, and CD25-deficient mice are subject to lethal autoimmunity." (PMID 34747370, 2021). "In MDA5+/- mice, CB4 infection also results in increased regulatory Foxp3+ CD4+ T cells at the site of autoimmunity." (PMID 34804036, 2021). "The immunomodulating activity is mediated both by the enhancement of regulatory T cells (important in autoimmunity) and in the induction of the transcription of FOXP3 (forkhead box P3 or scurfin), important in the control of regulatory T cells." (PMID 34070202, 2021). "Systemic loss of Treg cell function due to mutations in the Treg master regulator, FOXP3, leads to immune dysregulation, polyendocrinopathy, enteropathy, and X-linked (IPEX) syndrome, characterised by severe multi-organ autoimmunity." (PMID 33108502, 2021). "Immune suppression by Foxp3+ Treg cells is essential and indispensable for maintenance of tolerance and prevention of autoimmunity, as illustrated by spontaneous autoimmune disease development when Treg cells are rendered deficient." (PMID 34539668, 2021). "The administration of mAbs directed against CD25 as ‘surrogate’ Treg cell marker largely preserves systemic immune homeostasis and has been employed to examine the role of Foxp3+ Treg cells in the control of β cell autoimmunity." (PMID 34447385, 2021). "Treg cells during autoimmunity may receive ques from the inflammatory environment that imprint on their phenotype and function, leading to acquisition of an unstable phenotype due to either loss of Foxp3 expression or fragility with maintenance of Foxp3 expression." (PMID 34539668, 2021). "CD4+ FOXP3+ T regulatory (Treg) cells are key players in suppressing autoimmunity and maintaining self-immune tolerance." (PMID 34133541, 2021). "Here we revisited the effect of acute Foxp3+ Treg cell ablation on β cell autoimmunity in NOD mice in the context of a polyclonal TCR repertoire." (PMID 34447385, 2021). "Genetic mutations (e.g., FOXP3, RAG1, and AIRE) impact Treg thymic development and predispose individuals to autoimmune conditions." (PMID 34489935, 2021). "In this report, we provide novel evidence that pCons tolerance induces CD4+FoxP3+ T cells and potent regulatory B cells and granulocytes capable of suppressing autoimmunity in vitro in a murine model of SLE." (PMID 34093553, 2021). "DCs prevent tissue-destructive autoimmunity after heart injury by activating conventional fork-head box protein P3 (FOXP3)– CD4 + T helper cells and FOXP3 + CD4 + Treg cells." (PMID 33612829, 2021). "In contrast, under similar inflammatory conditions, USP7 deubiquitinating enzyme expressed in Treg cells, is downregulated resulting in Foxp3 degradation, while its conditional deletion in Treg cells leads to lethal autoimmunity." (PMID 34539668, 2021). "First developed for cancer immunotherapy, CARs demonstrated their feasibility in early pre-clinical studies in which CD4+FOXP3+ Treg specificity was redirected against antigen relevant to autoimmunity." (PMID 33708227, 2021). "Post translational or epigenetic modifications, affect Foxp3 protein expression and thus regulate Treg cell function and development of autoimmunity." (PMID 34539668, 2021).